TLL2 (tolloid like 2)
Description:
Protease which specifically processes pro-lysyl oxidase. Required for the embryonic development. Predominant protease, which in the development, influences dorsal-ventral patterning and skeletogenesis.
Tractability: Small molecule: a high-quality ligand is known. Antibody: UniProt places it where antibodies can reach, with high confidence; its Gene Ontology location is reachable by antibodies, with high confidence; UniProt predicts a signal peptide or a membrane-spanning region. PROTAC: ubiquitination databases record sites on it; a small molecule that binds it is known.
Target class: Enzyme; Hydrolase
Gene: Protein-coding gene on chromosome 10 (96,364,608 to 96,513,941, reverse strand). Ensembl gene ENSG00000095587.
Subcellular location: Secreted
Pathways (Reactome):
Extracellular matrix organization: Anchoring fibril formation; Collagen biosynthesis and modifying enzymes; Crosslinking of collagen fibrils; Degradation of the extracellular matrix
Gene Ontology:
Molecular function: metalloendopeptidase activity; serine-type endopeptidase activity; calcium ion binding; metallopeptidase activity; zinc ion binding
Biological process: collagen fibril organization; dorsal/ventral pattern formation; protein processing; proteolysis
Cellular component: extracellular region
Genetic constraint (gnomAD): Loss-of-function variants: 104 observed, 123.62 expected, observed/expected ratio (o/e) 0.84, 90% interval 0.72 to 0.99. The upper end of that interval is the gene's LOEUF score, 0.99, which puts it in group 4 of 6, group 1 being the genes least tolerant of losing a copy. Missense variants: 1,322 observed, 1,373.5 expected, observed/expected ratio (o/e) 0.96, 90% interval 0.92 to 1.01. Synonymous variants: 492 observed, 536.69 expected, observed/expected ratio (o/e) 0.92, 90% interval 0.85 to 0.99.
Homologues: Orthologues: chimpanzee TLL2 (99% identical), macaque TLL2 (97% identical), pig TLL2 (93% identical), dog TLL2 (92% identical), mouse Tll2 (90% identical), rat Tll2 (90% identical), guinea pig TLL2 (88% identical), rabbit TLL2 (54% identical). Paralogues in human: BMP1 (73% identical), TLL1 (72% identical), CUBN (16% identical), CNTNAP4 (15% identical), CNTNAP3 (15% identical), CNTNAP3B (15% identical), CNTNAP2 (14% identical), CNTNAP5 (14% identical), CNTNAP1 (13% identical), MEP1B (13% identical), F8 (12% identical), F5 (12% identical), and 23 more.
Diseases named in the same sentence as TLL2 in open-access papers:
TLL2 is named in the same sentence as 9 diseases in open-access papers, as found by Europe PMC text mining. Sharing a sentence is not in itself a finding about the gene and the disease. The quoted sentences say what the papers report.
attention deficit-hyperactivity disorder (1 paper, 2019). A disorder characterized by a marked pattern of inattention and/or hyperactivity-impulsivity that is inconsistent with developmental level and clearly interferes with functioning in at least two settings (e.g. at home and at school). "TLL2 encodes Tolloid-like protein 2 and is associated with attention-deficit/hyperactivity disorder." (PMID 31461406, 2019).
COVID-19 (1 paper, 2023). A disease caused by infection with severe acute respiratory syndrome coronavirus 2. "There was an increased deposition of collagen in COVID-19 lungs, with an early increased expression of genes linked to ECM orchestration and organization, such as Tolloid-like 2, ADAMTS8, and collagen III." (PMID 37964271, 2023).
muscular atrophy (1 paper, 2025). The loss of muscle tissue due to inactivity or disease. "Other relevant genes, such as TLL2, CH25H, and ST13, affect muscular atrophy and adipocyte differentiation." (PMID 41373569, 2025).
cancer (3 papers, 2019 to 2024). A tumor composed of atypical neoplastic, often pleomorphic cells that invade other tissues. "Both enzymes (TLL1 and TLL2) play a role in tissue remodeling and are upregulated in diverse human diseases, including chronic inflammatory disorders and cancer." (PMID 38396603, 2024). "Aberrant expression of neuropilin and tolloid-like 2 (NETO2) has been observed during the progression of some human carcinomas." (PMID 30770791, 2019).
intestinal diseases (1 paper, 2023). "Several of these genes, including Ralbp1, Pfas, Tyro3, Opcml, Syne2, Six4, Tll2, and Slc23a2, were previously implicated in gut microbiome abundance, metabolic traits, and several intestinal diseases." (PMID 37420306, 2023).
TLL2 also shares sentences with these, for which no sentence is quoted: breast carcinoma (1 paper); esophageal squamous cell carcinoma (1); spinal muscular atrophy (1); tumor (1).